LINC01060 (long independently transcribed non-coding RNA 1060)
Gene: Long non-coding RNA gene on chromosome 4 (188,400,569 to 188,681,051, forward strand). Ensembl gene ENSG00000249378.
Diseases named in the same sentence as LINC01060 in open-access papers:
LINC01060 is named in the same sentence as 5 diseases in open-access papers, as found by Europe PMC text mining. Sharing a sentence is not in itself a finding about the gene and the disease. The quoted sentences say what the papers report.
glioma (7 papers, 2021 to 2024). A benign or malignant brain and spinal cord tumor that arises from glial cells (astrocytes, oligodendrocytes, ependymal cells). "LINC01060 was aberrantly expressed in various cancers, including glioma and pancreatic cancer, and was significantly associated with poor clinical prognosis." (PMID 36700197, 2022). "Linc01060 was upregulated in gliomas and significantly correlated with tumor grade and poor clinical prognosis." (PMID 35999601, 2022). "Another recent study revealed that exosomes derived from hypoxic glioma stem cells contain an elevated level of Linc01060, which supports glioma progression by regulating the MZF1/c-Myc/HIF-1α axis and is correlated with a poor clinical prognosis." (PMID 34681857, 2021). "Overall, inhibiting Linc01060-containing SEVs or targeting the Linc01060/MZF1/c-Myc/HIF1a axis may be an effective therapeutic strategy for glioma." (PMID 35999601, 2022). "In glioma cells, Linc01060 promotes myeloid zinc finger 1 (MZF1) stabilization, enhanced c-Myc activity, and increased HIF1α levels, which in turn activate Linc01060 transcriptionally in a positive feedback loop." (PMID 39585046, 2024). "Linc01060 expression was significantly increased in hypoxic GSC (H-GSC), which promoted malignant proliferation of cells by transferring SEVs into glioma cells and leading to significantly higher Linc01060 expression in cells." (PMID 35999601, 2022).
pancreatic cancer (3 papers, 2021 to 2024). "Decreased expression of LINC01060 has been reported to be associated with the progression of pancreatic cancer by vinculin-mediated focal adhesion turnover." (PMID 38357948, 2024). "There is evidence that knockdown of Linc01060 could promote the progression of pancreatic cancer via the vinculin-mediated focal adhesion pathway turnover." (PMID 33614260, 2021).
cancer (2 papers, 2022). A tumor composed of atypical neoplastic, often pleomorphic cells that invade other tissues. "In particular, lncRNA GAS5, UNC5B-AS1, PARD6G-AS1, and LINC01060 have been widely reported in cancer and other diseases." (PMID 35360864, 2022).
tumor (2 papers, 2017 to 2022). "Interestingly, the qRT-PCR results indicated that the expression of AC012065.1, LINC01116, TMCC1-AS1 and LINC01060, was significantly higher in tumor tissue while expression of AC002511.2, LINC00426 and ARHGAP31-AS1 was similar between tumor and normal tissue." (PMID 36387100, 2022).
LINC01060 also shares sentences with these, for which no sentence is quoted: breast carcinoma (2 papers).